IL6 (interleukin 6)
Diseases named in the same sentence as IL6 in open-access papers (continued):
Sharing a sentence is not in itself a finding about the gene and the disease.
periodontitis (continued). "IL-6 and IL-8 have previously been reported in human gingival tissues in periodontitis patients and increased mRNA expression of TIMP-1 has been reported in gingival tissue from periodontitis patients following nonsurgical periodontal treatment." (PMID 30041453, 2018). "In this way, our study evaluated the role of anti-inflammatory (IL-10) and proinflammatory cytokines (IL-6) in chronic periodontitis patients." (PMID 29489938, 2018). "Locally delivered simvastatin was seen to play a positive role in chronic periodontitis treatment and impacts IL-6 mRNA levels." (PMID 30186882, 2018). "In this investigation, the periodontitis group showed higher salivary levels of IL-6 and TNF-α compared with periodontal healthy pregnant women." (PMID 29740515, 2018). "Markers of systemic inflammation, including C-reactive protein and interleukin 6, are surrogate markers of atherosclerotic vascular disease and are increased in patients with periodontitis." (PMID 30314398, 2018). "Particularly, IL-1β is known to be a major mediator of periodontitis, and triggers the pro-inflammatory cytokines, IL-6 and IL-8, in gingival fibroblasts and PDLFs." (PMID 30142971, 2018). "Gingival tissues in patients with periodontitis show greater increases in pro-inflammatory cytokines, such as IL-1, IL-6, IL-8, and TNF-α, as well as other inflammatory mediators, compared to gingival tissues in healthy individuals." (PMID 29401750, 2018). "Periodontal diseases are caused by gram-negative bacterial infections and pro-inflammatory cytokines, including IL-6, IL-8, and IL-1β, which appear to be major mediators of inflammation in periodontitis." (PMID 29932110, 2018). "Mean ± SD of IL-6 and IL-17 was highest in the severe periodontitis followed by moderate and mild CP, while the lowest concentration was in healthy controls." (PMID 29670909, 2018). "In this regard, some studies have shown that periodontitis can induce platelet aggregation and activation, together with an increase in the levels of inflammatory cytokines such as IL-6 and TNFa." (PMID 28676826, 2017). "IL-6 is thought to be involved in the immune response in many inflammatory diseases including periodontitis." (PMID 28597116, 2017). "Previous studies in humans have shown that elevated levels of some cytokines, such as IL-1β, IL-6, IL-21, and IL-23, are necessary for promoting Th17 differentiation and maintenance during the destructive phase of periodontitis." (PMID 28497028, 2017). "The effect of Δ12PGJ2 on periodontitis inhibited the production of interleukin-6 (IL-6) in osteoblast-like cells MC3T3E-1 incubated with LPS." (PMID 28678155, 2017). "A comparison between gingival tissues and peripheral blood samples from the same periodontitis patient showed that the methylation level of the IL-6 promoter was lower in gingival tissues." (PMID 29201597, 2017). "IL-6 and IFN-γ are pro-inflammatory cytokines that have been linked to the stimulation of osteoclastic resorption in periodontitis." (PMID 28326084, 2017). "In line with this, several studies in humans have shown elevated levels of IL-6 and IL-17 in inflamed gingiva, gingival crevicular fluid and plasma in patients with periodontitis." (PMID 28497028, 2017). "In order to compare the differences of salivary BPIFA1, TNF-α, and IL-6 concentrations among T2DM/NDM patients with periodontitis at different stages, we further divided the subjects into eight subgroups." (PMID 29109737, 2017). "The IL-6 promoter was found to be partially methylated in gingival tissue samples from both periodontitis patients and healthy individuals, but the expression of IL-6 was higher in periodontitis patients." (PMID 29201597, 2017). "The authors demonstrated that PAR1 expression was downregulated in chronic periodontitis patients and inversely correlated to gingival crevicular fluid levels of IL-6, IL-8, TNF-α, IFN-γ, and MMP-2." (PMID 28503577, 2017).
periodontitis (continued). "A negative correlation was found between methylation levels of IL-6 in gingival tissue and probing depth in periodontitis patients, compared to the positive correlation with TLR2 methylation and probing depth." (PMID 29201597, 2017). "Among these cytokines, IL-6 is a pro-inflammatory cytokine which highlights the importance in periodontitis." (PMID 27834922, 2016). "Clinical studies have shown increased levels of IL-6 in gingival tissues of patients with periodontitis compared with healthy controls." (PMID 27807462, 2016). "In the GCF, the background levels of both IL-1β and IL-6 were highly and equally elevated, while IL-10 values were decreased in the periodontitis groups as compared to healthy controls." (PMID 26977121, 2016). "The expression of IL-6 has been shown to be higher in periodontal inflammation sites and to be closely related to the clinical severity of periodontitis." (PMID 26859747, 2016). "Interleukin‐6 (IL‐6) is secreted by various cell types and has been shown to be important pro‐ and anti‐inflammatory mediator involved also in the pathogenesis of periodontitis by regulating the expression of IL‐1 and tumor necrosis factor alpha (TNF‐α)." (PMID 29744169, 2016). "Among these cytokines, IL-6 and IL-8 are considered to be crucial pro-inflammatory factors correlated with the initiation of periodontitis." (PMID 27834922, 2016). "The role of IL-1, IL-6, IL-8, and IL-12 has previously been established in periodontitis proving their definitive role in periodontal destruction." (PMID 26998377, 2016). "Patients with periodontitis also displayed higher serum levels of IL-6 and TNF-α than the periodontally healthy individuals." (PMID 27111223, 2016). "While this occurs naturally as part of normal bone remodeling, excess IL-6 production, as during periodontitis, leads to the destruction of alveolar bone." (PMID 26859747, 2016). "Gingival tissues of chronic periodontitis patients exhibit significantly higher levels of pro-inflammatory cytokines IL-1, IL-6, IL-8 and TNFα than those of periodontally healthy patients." (PMID 27035339, 2016). "nucleatum had significantly increased circulating CRP levels (p = 0.020) compared to controls while the mice with induced periodontitis had increased levels of IL-6 (p = 0.047) and IL-8 (p = 0.105)." (PMID 25806806, 2015). "The β values of IL-1β and IL-6 were 2.04 and 0.34, respectively, indicating that these 2 proinflammatory cytokines significantly increased with the severity of periodontitis." (PMID 25884025, 2015). "CRP, elastase, lipopolysaccharide binding protein, and IL-6 levels were elevated in patients with untreated aggressive periodontitis compared to healthy control group." (PMID 26346216, 2015). "Consistent with this, IL-6 levels were below the level of detection in the assay (0.64 pg/mL) in approximately 2% of the periodontitis patients, compared with nearly 20% of both gingivitis and healthy subjects." (PMID 26347856, 2015). "It would be useful to further investigate IL-6 as a novel therapeutic target for improving periodontitis treatment efficacy in future studies." (PMID 25884025, 2015). "Both naproxen and ATB-346 inhibited the increase of gingival IL-1β and IL-6 secondary to periodontitis, but IL-10 was unaffected." (PMID 25755876, 2015). "Recent studies have shown that IL-6 is significantly higher in patients with chronic periodontitis than in healthy controls." (PMID 25884025, 2015). "It has been well recognized that both periodontitis and RA are associated with persistent high levels of pro-inflammatory cytokines including TNF-α, IL-1, and IL-6." (PMID 25657893, 2015). "In this study, the AUC of the difference in IL-6 after scaling was 0.90, suggesting that the difference in IL-6 is an effective biomarker for predicting the periodontitis treatment outcome." (PMID 25884025, 2015).
periodontitis (continued). "Other clinical data indicate that IL-6 levels are higher in refractory periodontitis, and increased granulocyte chemotactic factor (GCF) levels correlate to gram-negative fimbriae." (PMID 25888355, 2015). "It has also been documented that systemic (serum) and local (GCF and saliva) levels of IL-6 are increased in patients with periodontitis than those in the healthy controls." (PMID 25657893, 2015). "Several studies have reported the systemic and local production of IL-6 and its signaling mediators in patients with periodontitis [57, 58•]." (PMID 25657893, 2015). "The classification performance measures using the pair (IL-1ß, IL-6) was especially pronounced indicating that these molecular markers play a critical role in discerning periodontitis from gingivitis and health." (PMID 26347856, 2015). "Serum concentrations of IL‐6 were decreased following periodontal treatment in patients with periodontitis." (PMID 29744142, 2015). "The differences of IL-6 levels (cutpoint: 0.05 μg/g) yielded a sensitivity and specificity of 90.0% and 81.82%, respectively, forpredicting the periodontitis treatment outcome." (PMID 25884025, 2015). "In this study, significant correlations were also observed between salivary IL-6 and IL-1β (r = 0.72 and P < 0.01) of patients with periodontitis." (PMID 25884025, 2015). "Circulating TNF-α and IL-6 are also thought to become elevated as a result of intrauterine infections in humans, however our results showed that only IL-6 was significantly increased in mice with induced periodontitis." (PMID 25806806, 2015). "The local expression of IL-6 and its relation with the IL6 c.-174G>C polymorphism and periodontitis was also analyzed." (PMID 25548674, 2014). "Higher levels of IL-6 were detected in the sera of patients with periodontitis compared to healthy controls." (PMID 24741613, 2014). "Our results indicated that recombinant APN treatment decreased mRNA expression of the proinflammatory cytokines including TNF-α, IL-1, and IL-6 in WAT isolated from DIO mice induced with periodontitis (P<0.05)." (PMID 24836538, 2014). "Over the course of 4 months, the mice exhibited lipid stripes in which the presence of Porphyromonas gingivalis was detected, and in mice with periodontitis, higher serum levels of IL-6 and VCAM-1 in aorta were detected." (PMID 24741613, 2014). "IL6 gene promoter and COX-2 polymorphisms are some of a few promising genetic variants studied in association with periodontitis in different populations." (PMID 24551049, 2014). "The dosage of the cytokine IL-6 in saliva held in the sample revealed a statistically significant difference in expression between patients with periodontitis compared to those with evidence of periodontal health." (PMID 25548674, 2014). "Conversely, the level of IL-6 was relatively high in both patients with periodontitis and healthy controls." (PMID 25530681, 2014). "Al-Ghurabei has documented that serum levels of hs-CRP and IL-6 were significantly elevated in patients with chronic periodontitis as compared to healthy control group." (PMID 24526921, 2014). "IL-6 showed higher concentrations in the serum (about 95 pg/mL) than IL-1β in the LPS-periodontitis rats, and, again, CMC 2.24 appeared to reduce the level of this cytokine." (PMID 25104884, 2014). "While this occurs naturally as part of normal bone remodeling, an excess of IL-6 production, as found during periodontitis, leads to the destruction of alveolar bone." (PMID 24877093, 2014). "Systemically, periodontitis results in higher levels of several inflammatory mediators, such as IL-6 and TNF-α, in response to the challenge promoted by the oral biofilm." (PMID 25688342, 2014). "Similar findings of higher expression of IL-6 in periodontal tissues from chronic periodontitis were recently reported." (PMID 23874838, 2013). "The data from the present study revealed that IL-6 was expressed in the gingival tissue of each of the 19 patients with periodontitis." (PMID 24137277, 2013).
periodontitis (continued). "In conclusion, the levels of three cytokines (TNF-α, IL-6 and IL-8) in the human gingival tissues of 19 patients with periodontitis were detected by ELISA." (PMID 24137277, 2013). "Circulating levels of CRP and IL-6 were significantly higher in the periodontitis subjects with hypertension, than in the control group." (PMID 23009606, 2012). "In patients with refractory periodontitis, active sites—those displaying loss of attachment >2.1 mm in 3 months—revealed significantly higher GCF IL-6 levels than inactive ones." (PMID 22114600, 2012). "Thus, IL-6 -174 G/C genotype may be considered a risk genotype for periodontitis susceptibility." (PMID 23046796, 2012). "According to our results, increased expression of IL-6 has been described in diabetic patients with periodontitis." (PMID 22611374, 2012). "Periodontitis produces bacteraemias and the host responds with elevated levels of interleukin-6 (IL-6), known to induce hepatocytes to produce CRP and other acute-phase proteins and pro-coagulant mediators." (PMID 22322513, 2012). "Several reports have suggested a relationship between the progression of periodontitis and the expression of interleukin-1 (IL-1), IL-6, IL-8, and tumor necrosis factor-α in gingival tissues." (PMID 22131647, 2011). "Several reports have suggested a relationship between the progression of periodontitis and the expression of interleukin-1 (IL-1), IL-6, IL-8 and tumour necrosis factor-α in gingival tissues." (PMID 21253492, 2010). "Spontaneous production of IL-6 has been reported in mononuclear cells isolated from inflamed gingival tissues of patients with periodontitis." (PMID 20407653, 2009). "CRP, IL-1β, IL-6, and TNF-α have been associated with the presence of various bacterial infections, including periodontitis." (PMID 20407653, 2009). "The aim of the present study was to investigate systemic levels of inflammatory markers of cardiovascular diseases like C-reactive protein and interleukin-6 in patients with chronic periodontitis, in comparison to periodontally healthy individuals." (PMID 20407653, 2009). "As IL-6 is a systemic marker of cardiovascular diseases, this was also used in this study to evaluate its relationship between periodontitis and cardiovascular diseases." (PMID 20407653, 2009). "Due to the potential association between periodontitis and cardiovascular disease, CRP and IL-6 have been identified as risk factors for cardiovascular disease." (PMID 20407653, 2009). "In the paper that compared cytokine levels for 54 periodontitis patients and 40 healthy controls, cytokines IL‐1β, IL‐4, IL‐6, IL‐10, IL‐17A, IL‐17F, IL‐21, IL‐22, IL‐23, IL‐25, IL‐31, IL‐33, IFN‐γ, sCD40L and TNF‐α were measured in saliva and serum at baseline, 3, 6 and 12 months after treatment." (PMID 41580300, 2026). "Chronic inflammation in periodontitis and gingivitis reflects an imbalance between pro-inflammatory and anti-inflammatory signaling, driven by elevated pro-inflammatory cytokines and chemokines, such as IL-6, TNF-α, and IL-1β." (PMID 41516397, 2026). "Our findings expand on this understanding, demonstrating that JAK inhibitors reduce bone resorption and the mRNA expression of inflammatory mediators relevant to periodontitis progression, including Il‐6, Rankl, and Tnf‐α, while also reducing osteoclast numbers." (PMID 41041963, 2025). "Furthermore, inflammatory cytokines, such as C-reactive protein, tumor necrosis factor-α, immunoglobulin G, interleukin-1β, and interleukin-6, are released in response to periodontitis." (PMID 40907543, 2025). "Given the central role of inflammation in periodontitis and the bidirectional relationship between local and systemic immune responses, evaluating salivary IL-6 and irisin levels may offer valuable clinical insights." (PMID 41007333, 2025). "Notably, IL-6 and TNF-α are two key cytokines that significantly contribute to the inflammatory process associated with periodontitis." (PMID 40085302, 2025).
periodontitis (continued). "This study aimed to evaluate the association between periodontitis stage and grade with systemic levels of C-reactive protein (CRP), interleukin-1β (IL-1β), interleukin-6 (IL-6), and tumor necrosis factor-alpha (TNF-α) and assess changes following standardized non-surgical periodontal therapy." (PMID 41440349, 2025). "As a result of the study, GLE down-regulated the expression levels of pro-inflammatory mediator proteins increased by PG-LPS in a concentration-dependent manner, and increased gene levels of il-6, il-1β, and tnf-α, the major pro-inflammatory cytokines in periodontitis." (PMID 40733170, 2025). "Mechanistic studies further reveal that chronic periodontitis exhibits pathophysiological synergism with cardiovascular disease determinants mediated by circulating mediators including interleukin-6 (IL-6), tumor necrosis factor-alpha (TNF-α), and high-sensitivity C-reactive protein (hsCRP)." (PMID 40722812, 2025). "Based on these findings, we can postulate that IL-6 contributed by periodontitis may build up within the body due to renal excretion impairment caused by worsening renal function." (PMID 40452929, 2025). "Similarly, in SLE, periodontitis contributes to an elevated inflammatory burden, as systemic levels of cytokines like IL-6 and IL-17 are increased, intensifying immune dysregulation." (PMID 39852378, 2025). "Additionally, periodontitis induced elevated gingival IL-6 and CXCL2 levels in a rat model of tooth movement." (PMID 40724937, 2025). "However, during inflammatory conditions, abundant in pro‐inflammatory cytokines such as IL‐6 as observed during periodontitis and PI, Tregs can lose their typical regulatory phenotype and acquire a pro‐inflammatory and osteolytic profile, instead." (PMID 40856197, 2025). "Similarly, low birth weight labor is linked to periodontitis through intermediary pro-inflammatory cytokines and chemokines, namely TNF-α, IL-1β, CRP, IL-1, IL-6 and IL-18." (PMID 41394354, 2025). "Neither IL-1β nor IL-6 demonstrated significant independent associations with Grade C periodontitis in the multivariate analysis." (PMID 40843742, 2025). "They found that salivary Trp, Kyn, KynA, IL-6, PA, and QA levels were significantly higher in periodontitis (p-value < 0.05) compared to healthy controls, alongside increased clinical indicators of disease severity (e.g., probing depth, clinical attachment loss, and bleeding on probing)." (PMID 41002365, 2025). "Additionally, these antibodies significantly reduced the transcript levels of the pro-inflammatory cytokines IL-1β and IL-6, which are markers of periodontitis." (PMID 39699191, 2025). "This phenomenon may be attributed to the acute inflammatory response of local tissues to injury in the early stages (1 day) after periodontitis induction, during which IL-6, involved in the acute inflammatory response, reacts rapidly." (PMID 40799647, 2025). "The marked increase in IL-6 expression indicates that periodontitis may influence distant tissues through systemic inflammatory responses." (PMID 40647479, 2025). "Periodontitis, characterized by chronic bacterial infection and subsequent host inflammatory response, triggers the release of pro-inflammatory cytokines including interleukin-1β (IL-1β), interleukin-6, and tumor necrosis factor-α (TNF-α)." (PMID 41153725, 2025). "IL-6 showed satisfactory diagnostic performance in separating gingivitis patients from those with periodontitis and identifying early (Stage I + II) and advanced (Stage III + IV) stages of periodontitis." (PMID 41280712, 2025). "Severe periodontitis leads to an increase in the levels of C-reactive protein, interleukin- 1 (IL- 1), and IL-6, which may work synergistically with the toxins in cigarette smoke to exacerbate inflammatory changes in tissues and organs." (PMID 39582409, 2025).